INS (insulin)
Diseases named in the same sentence as INS in open-access papers (continued):
Sharing a sentence is not in itself a finding about the gene and the disease.
Hyperglycemia (continued). "Firstly, some AF derivatives have been reported to lower hyperglycaemia in diabetic animals independent of insulin secretion and hyperlipidaemia." (PMID 31680948, 2019). "Next, bolus insulin, restarted with altered formulations comprised of regular human insulin or insulin lispro, inhibited neither postprandial hyperglycemia nor morning hypoglycemia." (PMID 30621663, 2019). "Decreased acute phase insulin responses to glucose and transient postprandial hyperglycemia which is not captured by HbA1c must have resulted in fetal hyperinsulinemia and ensuing fetal adiposity during early pregnancy." (PMID 31841546, 2019). "Insulin helps the blood glucose level to be a normal circumstance and not turn into hyperglycemia or hypoglycaemia." (PMID 31316568, 2019). "The findings of this randomized, placebo-controlled trial suggest a significant amelioration of dyslipidemia and insulin sensitivity after 90 days of BPE-C supplementation to a group of MetS patients characterized by an elevated AIP (over 0.34) and moderate hyperglycemia (up to 130 mg/L)." (PMID 31167512, 2019). "In diabetic patients, due to abnormal metabolism of insulin, cells and tissues do not use blood glucose, resulting in hyperglycemia, and these patients can develop other metabolic and functional complications." (PMID 31717560, 2019). "This provides further evidence that postprandial hyperglycaemia develops when beta cell insulin secretion and reduced insulin clearance can no longer compensate for insulin resistance." (PMID 31489455, 2019). "Pancreatic β-cell malfunction is characterized by the lack of insulin production and secretion to regulate glucose metabolism, which results in hyperglycemia in PDX-1 knockout mice and IRS-2 knockout mice." (PMID 31627434, 2019). "Currently, the development of a multitude of intravenous insulin protocols in the ICU is lacking a unified optimal protocol to control hyperglycemia." (PMID 31052277, 2019). "Tamoxifen had modest effects upon glucose homeostasis of mixed genetic background (F1 B6129SF1/J) mice, with fasting hyperglycemia and improved glucose tolerance but without overt effects on fed glucose levels or insulin sensitivity." (PMID 31490929, 2019). "Although inhaled insulin is used before each meal and does not substitute long acting insulin it has been shown to decrease not only postprandial, but also fasting, hyperglycemia." (PMID 31470605, 2019). "This is because basal hyperglycemia in the diabetic patient provides a glucose concentration gradient that drives these facilitative transporters even in the absence of insulin-stimulated glucose transport." (PMID 30962478, 2019). "ANP reduced insulin-induced PCSK9, especially in the context of a medium simulating hyperglycemia." (PMID 30634533, 2019). "Our results indicate that efferent vagal stimulation attenuates hyperglycemia in endotoxemia by inducing insulin and regardless of TNF regulation." (PMID 30700738, 2019). "The present study demonstrated that the various indices of insulin sensitivity are reduced to comparable levels in patients of acromegaly irrespective of the presence or absence of hyperglycaemia." (PMID 30948746, 2019). "The safety is intended as the ability of the algorithm not to produce rebounds in hyperglycemia and adverse events, like diabetes ketoacidosis, that can result from an extended suspension of basal insulin delivery." (PMID 30922295, 2019). "Concerning hyperglycemia classification and detection, RNN, GP, HMM, feedforward ANN, GA, and hybrid systems have been developed and tested, exploring various types of input parameters including BG, insulin, heart rate, and QT interval." (PMID 31042157, 2019). "Through this study, a conclusion could be made that WEM mitigates hyperglycemia, IR, and inflammation through the interactions among TLR2 signalling pathway, insulin signalling pathway and TNF-α." (PMID 31752797, 2019).
Hyperglycemia (continued). "While modern insulin analogues, rt-CGM and hybrid closed-loop systems all contribute to reducing hypoglycaemia in pregnancy, optimising hyperglycaemia requires early prandial bolus insulin (30–45 min before meals in late gestation) and meticulous attention to dietary intake for meals and snacks." (PMID 31161344, 2019). "We next questioned whether the hyperglycemia and glucose intolerance observed in sedentary SMA mice could be attributed to a reduced insulin sensitivity." (PMID 31632295, 2019). "All 66 patients recovered from their hyperglycemia with treatment - 53 remained insulin dependent and the outcomes of 13 were not reported." (PMID 30693099, 2019). "The high-fat diet alone only tended to increase leptin and insulin levels while it did induce hyperglycemia, but no significant increase of HOMA-IR." (PMID 31332243, 2019). "Results from the OGTT suggested a possible anti-hyperglycemia property for the CGN and SCGN, which may be due to the increase, albeit insignificant, in the circulating insulin level." (PMID 31117266, 2019). "In conclusion, a lack of uPA impairs insulin secretion and regeneration of β cells in mice and cell models and induces hyperglycemia." (PMID 31756973, 2019). "While the insulin therapy corrected hyperglycemia in the diabetic mice, it did not restore Pomc or Mc4r expression in ARC or PVH, respectively." (PMID 30503832, 2019). "Furthermore, the combination of sucrose or sucralose with a high fat diet aggravated the insulin signaling pathway in white adipose tissue, decreasing the abundance of GLUT-4, resulting in hyperglycemia." (PMID 31010163, 2019). "Although the total amounts of secreted insulin and C-peptide were increased, the levels of insulin were not sufficient to compensate for hyperglycemia." (PMID 29957055, 2019). "Conversely, in the absence of insulin (e.g., where the individual has removed their insulin pump or when insulin delivery is blocked or skipped), any level of exercise can lead to hyperglycemia and ketone formation." (PMID 31835538, 2019). "In a previous study, hyperglycemia occurred in pigs that became diabetic after insulin-producing cells were destroyed, and there were no adverse effects on the kidney and liver functions." (PMID 29879811, 2019). "Although Lentinus edodes did not reduce the mother-fetus hyperglycemia, it promoted an improvement in maternal glucose tolerance and an increase in insulin levels." (PMID 31717560, 2019). "Although our model was able to induce a marked increase in body weight, we did not observe a constant hyperglycemia and animals had no need for insulin treatment." (PMID 31681334, 2019). "A retrospective study showed suboptimal glucose control using intravenous insulin infusion to treat parenteral nutrition-related hyperglycaemia in the non-intensive care setting." (PMID 30935872, 2019). "It has been observed that glycaemic control by insulin in the patient with hyperglycaemia in stroke, in studies like THIS (Treatment of Hyperglycaemia in Ischemic Stroke) or GRASP (Glucose Regulation in Acute Stroke Patients), produces an improvement in complications and long-term evolution." (PMID 31052350, 2019). "Basal plasma insulin concentrations were 4-fold higher in the obese than the lean subjects (P = 0.008) and increased 5-fold during hyperglycemia in both groups, independent of changes in plasma acetate concentrations." (PMID 31404159, 2019). "The harmful impact of hyperglycemia and lack of insulin production on the liver, heart, brain, pancreas, and retinal cells of the eye were also alleviated by HT." (PMID 31234300, 2019). "Taken together, these results provide evidence of a dorsal hindbrain mechanism for rapidly induced hyperglycemia, independent of insulin." (PMID 30804396, 2019).
Hyperglycemia (continued). "The inability of glucose to stimulate insulin secretion appears to be the central abnormality leading to the severe hyperglycemia with or without ketoacidosis and persists for several days to weeks despite normalization of the plasma glucose." (PMID 30280274, 2018). "db/db+Ex mice still exhibited hyperglycemia, hyperinsulinemia, and impaired glucose tolerance, indicating that moderate exercise training was not able to improve insulin sensitivity." (PMID 29896118, 2018). "Patients using this method have greater flexibility in food choices without the concern of postprandial hyperglycemia given that the amount of carbohydrates ingested is considered when computing the amount of insulin to be administered before meals." (PMID 29791661, 2018). "The most effective approach for managing hyperglycemia in hospitalized noncritically ill patients, including postoperative patients, is basal-bolus insulin therapy." (PMID 29255628, 2018). "This retarded weight gain is a direct result of the degree of hyperglycemia, as it is not evident at a milder hyperglycemia, and is preventable by insulin replacement." (PMID 30348168, 2018). "AC also reduced the postprandial hyperglycemia in healthy W rats by increasing serum insulin levels, however, without inducing a hypoglycemic state." (PMID 29342984, 2018). "Correction insulin alone – the so-called sliding scale – does not provide sufficient control of hyperglycemia." (PMID 29255628, 2018). "In this regard, DAG may play a role in the activation of PKC which then inhibits insulin activation of IRS and subsequently its initiated signaling, thereby leading to the development of hepatic IR and hyperglycemia." (PMID 29614722, 2018). "Thus, the ameliorating effects of HS on hyperglycemia and glucose intolerance in WBKDF rats are unlikely due to the increase in plasma insulin levels." (PMID 29744365, 2018). "Together, our results indicate that the maintained expression of Neurog3 in neogenerated β-like cells does not alter their function, such cells secreting insulin and being able to counter the consequences of glucose-induced hyperglycemia." (PMID 30092080, 2018). "Larger observational studies are needed to compare patients with similar hyperglycemia profiles with and without insulin treatment to ascertain an insulin treatment effect." (PMID 30025516, 2018). "A greater body of literature also indicates increased proliferation in response to autoimmune response, rather than increased insulin demand due to hyperglycemia, which further confirms the possible role of epitope spreading in accelerated autoimmunity." (PMID 29320541, 2018). "Previous studies have suggested that neither peripheral tissue insulin resistance nor glucolipotoxicity fully explain the onset of beta cell dysfunction showing a delayed and insufficient insulin section to hyperglycemia in T2D." (PMID 29587416, 2018). "We found that larvae with reduced expression of key DILPs fed normally on Coomassie-dyed 20% sucrose despite hyperglycemia, while larvae with activated insulin signaling were euglycemic but did not eat." (PMID 30271990, 2018). "It is worth to notice that we suggest possible regulatory effects of blood amylase only on post-prandial hyperglycaemia and insulin response, not on the basal plasma levels of glucose and insulin." (PMID 29874296, 2018). "Many studies showed the efficacy of insulin-only CLS devices in increasing the time spent in normal glycaemia and reducing hypoglycaemia and hyperglycaemia compared to SAPs in adults, but there are few studies in the paediatric population, in particular in young children." (PMID 29954380, 2018). "This improvement resulted from a reduction of time spent in hyperglycaemia without change in total insulin delivery." (PMID 30292578, 2018). "Continuous high-fat-diet feeding without any intervention resulted in further progress in hyperglycaemia, hyperinsulinaemia, decreased insulin sensitivity, and increased BW in the DC group." (PMID 30199540, 2018).
Hyperglycemia (continued). "Insulin-secreting β-cells become nonfunctional in T1DM, and this condition primarily arises due to autoimmune destruction of cells causing hyperglycemia." (PMID 30046616, 2018). "Intermittent leucine deprivation significantly reduces hyperglycemia in db/db mice independent of body weight change, together with improvement in glucose tolerance and insulin sensitivity." (PMID 30294696, 2018). "Available treatment strategies, which are mainly based on treating hyperglycemia, with insulin and other pharmacological agents are not completely efficient and can even lead to development of unwanted side effects." (PMID 30563087, 2018). "IRS2−/− mice had higher non-fasting levels of plasma insulin (9 ± 1 vs. 20 ± 2 μU/ml, p < 0.01) and exhibited fasting hyperglycemia (5.3 ± 0.57 vs. 12.6 ± 2.7 mMol/l, p < 0.05) than IRS2+/+." (PMID 29628894, 2018). "This was followed by sustained hyperglycemia, independent of changes in insulin and glucagon levels, in glucose disposal, or in the ability of insulin to suppress lipolysis." (PMID 29528284, 2018). "The beta cells of patients with severe hyperglycemia with or without ketosis have lost the ability of exogenous or endogenous glucose to stimulate β-cell insulin secretion." (PMID 30280274, 2018). "In contrast, 30 mg/kg STZ was sufficient to induce an impaired insulin response to glucose and hyperglycemia, without changing the body weight, insulin sensitivity, pancreatic insulin content, or β-cell area." (PMID 29854823, 2018). "The in vivo experiments showed that a single oral administration of AC contributed to control the hyperglycemia in GK rats, by reducing the non-fasting glycaemia and improving the glucose tolerance through increase of the serum insulin levels." (PMID 29342984, 2018). "Insulin-mediated tight glycemic control (IIT) significantly decreased TBARS concentrations by 15%, as compared to conventional insulin treatment (CIT) and moderate hyperglycemia." (PMID 29300728, 2018). "In this study, we observed that non-hypertensive non-obese T2DM (GK) rats exhibited hyperglycemia and hyperlipidemia, inefficient production of insulin and GLP-1, and also cardiac dysfunction." (PMID 29325553, 2018). "As a result, the organism is no longer able to produce insulin and develops hyperglycaemia and, if untreated, death." (PMID 31225479, 2018). "It does not affect insulin production in the pancreas, but is more likely to reduce hyperglycemia, by activation of AMP-activated protein kinase (AMPK)." (PMID 30245847, 2018). "The constant need for insulin production eventually reaches non-sustainable levels for the pancreas and insulin levels start to drop—it is at that point that hyperglycemia ensues." (PMID 29483947, 2018). "Treatment with S961 resulted in hyperglycemia and hyperinsulinemia but did not affect corticosterone levels, indicating that circulating insulin and corticosterone levels are regulated independently of each other." (PMID 30532187, 2018). "To examine the translational potential of using a PARP-1 inhibitor to treat the sequelae of hyperglycemia in humans, we used the NCI-H716 enteroendocrine cell line that is widely used to study human GLP-1-secretion, an important modulator of insulin production." (PMID 29392078, 2018). "In the study examining the acute (first-phase) insulin response to intravenous glucose, a paradoxically nonpositive insulin response had also been observed in subjects with fasting hyperglycemia." (PMID 29765987, 2018). "Metformin controls hyperglycemia by reducing hepatic glucose production and improving peripheral insulin sensitivity without weight gain or hypoglycemia." (PMID 29411291, 2018). "The two pancreatic parameters indicate Q1 and Q4 had different sensitivities to reduction in capacity of insulin production in response to chronic hyperglycemia, while the parameters related to insulin resistance were not different." (PMID 29444133, 2018).
Hyperglycemia (continued). "Indeed, muscle-specific deletion of GLUT4 promotes insulin resistance, glucose intolerance and hyperglycemia; whereas muscle-specific GLUT4 overexpression in diabetic animals improves insulin sensitivity and glycemic control." (PMID 30258406, 2018). "Therefore, insulin and leptin resistance of HFD AD mice lead to hyperleptinemia, hyperglycemia, and hyperphagia in a vicious cycle and ultimately the worsened metabolic stresses." (PMID 30096853, 2018). "β-cell specific CaV1.2−/- mice exhibit mild basal hyperglycemia, impaired glucose tolerance and lack of first-phase insulin secretion, but this important role in mammalian glucose-induced insulin secretion has not been assessed in zebrafish." (PMID 30521410, 2018). "However, compared to changes in controls, participants in the Mediterranean diet arm had no significant changes in any of the inflammatory biomarkers or adipokines (IL-6, IL-8, CRP, and adiponectin), markers of hyperglycemia (FPG and insulin), or FMD." (PMID 30271610, 2018). "Although our model was well suited for assessing the effects of hyperglycemia, it did not account for the other components of neonatal hyperglycemia in human preterm infants, including dextrose infusion and treatment with insulin." (PMID 29544513, 2018). "Exogenous insulin does not adequately regulate hyperglycemia nor prevent hepatic gluconeogenesis in these infants." (PMID 29180355, 2018). "Although many patients did receive intraoperative insulin treatment and these data are reported, the logistic regression did not include insulin treatment as a covariate because insulin treatment is a marker of hyperglycemia itself." (PMID 30025516, 2018). "Insulin and hyperglycemia are not the only possible factors so far correlated to the underlying pathogenetic mechanism of DAA." (PMID 30618774, 2018). "NAC administration in diabetic rats (DM+NAC) was shown raise insulin (not shown) and reduced hyperglycemia." (PMID 29796316, 2018). "In the present study, we have selected the T1DM rat model to study the effect of hyperglycemia and lack of insulin on cardiac mitochondrial energetics and transcription." (PMID 30487434, 2018). "From an evolutionary perspective, hyperglycemia is thought to be desirable as it provides glucose to cells that do not rely on insulin for glucose uptake, such as neurons and leukocytes." (PMID 29976786, 2018). "In the first 24 h both doses of insulin had statistically higher odds of hyperglycemia however oral medications did not." (PMID 30410577, 2018). "The absence of insulin leads to hyperglycemia and the release of free fatty acids from the adipose tissue, which are metabolized to ketone bodies (acetoacetateand β-hydroxybutyrate)." (PMID 29517669, 2018). "In such metabolic milieus, the insulin concentrations in the plasma are inadequate to compensate for hyperglycemia and fails to suppress hepatic gluconeogenesis." (PMID 29295584, 2017). "It is worth noting that Type I diabetes is the result of autoimmune destruction of the insulin-producing β-cells of the pancreas and is mainly characterized by lack of insulin, triggering the development of severe hyperglycemia." (PMID 28422055, 2017). "Exposed to high glucose over time, islet microtissues cultured in the absence of liver spheroids had reduced ability to release insulin, indicating that the prolonged hyperglycaemia impaired islet function." (PMID 29097671, 2017). "The occurrence of hypoglycemia and hyperglycemia during the first days after transition to continuous subcutaneous insulin infusion (CSII) in patients with type 1 diabetes has not been systematically studied in children." (PMID 28484424, 2017). "Insulin clamp studies showed that bursts of hyperglycemia, rather than constantly maintained levels of hyperglycemia, induced significant increases in fetal arterial plasma insulin levels." (PMID 28280744, 2017).